POLH (DNA polymerase eta)
Diseases named in the same sentence as POLH in open-access papers (continued):
Sharing a sentence is not in itself a finding about the gene and the disease.
cancer (23 papers, 2017 to 2025). A tumor composed of atypical neoplastic, often pleomorphic cells that invade other tissues. "ATR haploinsufficiency, arising due to somatic mutations in one allele, is frequent in certain cancers, presenting therapeutic opportunities for POLH inhibition." (PMID 38068959, 2023). "Co-inhibition of POLH and the ATR serine/threonine kinase, another DDR protein, causes synthetic lethality in a range of cancers, reinforcing that POLH is an emerging target for the development of novel oncology therapeutics." (PMID 34900730, 2021). "POLH overexpression has been linked to the development of chemoresistance in several cancers, including lung, ovarian, and bladder." (PMID 34900730, 2021). "POLH deficiency may thus drive the higher cancer incidence among XP-V patients via multiple mechanisms." (PMID 35935942, 2022). "Notably, ATR inhibitors are progressing well in the clinic, and ATR haploinsufficiency, arising due to somatic mutations in one allele, is frequent in certain cancers, presenting therapeutic opportunities for POLH inhibition." (PMID 34900730, 2021). "POLH-deficient cells are even more sensitive (10-fold) to gemcitabine/cisplatin combination treatment, which is a commonly used clinical regimen for treating a wide spectrum of cancers, including bladder, pancreatic, ovarian, cervical, and non-small-cell lung cancers." (PMID 38068959, 2023). "As a result, disruption of PCNA mono-ubiquitination impairs the lesion bypass function of polymerase eta (POLH/RAD30A; Polη), leading to the accumulation of unrepaired DNA damage and ultimately triggering apoptosis in OvCa cancer stem cells (CSCs)." (PMID 41008855, 2025). "The strategic downregulation of POLH in these cases re-sensitizes cancer cells to cisplatin treatment, supporting the targeting of the polymerase in certain situations of acquired drug resistance." (PMID 38068959, 2023). "In standard-of-care cancer therapies that involve platinum-based clinical agents, e.g., cisplatin or oxaliplatin, POLH can also bypass platinum-DNA adducts, negating the benefits of the treatment and enabling drug resistance." (PMID 38068959, 2023). "We prepared EBV-transformed cell lines from the primary lymphocytes of 3 patients bearing candidate variants (henceforth referred to as the POLD1/POLH cell line, POLE cell line, and POLK cell line) and from several age-and gender-matched cancer-free controls." (PMID 37095444, 2023). "DNA polymerase eta (POLH), as the Y‐family of DNA polymerases, mediates DNA translation synthesis and is associated with cisplatin resistance in cancer, which can be regulated by RNA modification." (PMID 37090117, 2023). "The suppression of POLH expression also enhances the cisplatin-induced apoptosis of cancer stem cells isolated from both ovarian cancer cell lines and primary tumors." (PMID 38068959, 2023). "Suppression of POLH expression also enhances cisplatin-induced apoptosis of cancer stem cells isolated from both ovarian cancer cell lines and primary tumors." (PMID 34900730, 2021). "In standard-of-care cancer therapies involving platinum-based clinical agents, e.g., cisplatin or oxaliplatin, POLH can bypass platinum-DNA adducts, negating benefits of the treatment and enabling drug resistance." (PMID 34900730, 2021). "Strategic downregulation of POLH in these cases re-sensitizes cancer cells to cisplatin treatment, supporting targeting of the polymerase in certain situations of acquired drug resistance." (PMID 34900730, 2021). "The POLH locus is primarily amplified in cancers, and this amplification is correlated with increased mRNA expression." (PMID 30347795, 2018). "In light of this, three mutational signatures, including PolH-related SBS9, unknown SBS34, and the so-called artifact SBS56, were found to be determined by A3C-H/AICDA mRNA levels across both genomes and cancer types." (PMID 38965255, 2024).
cancer (continued). "The POLH genotype could be important in the response of tumours to DNA damaging cancer chemotherapeutics, particularly as cancer genomics databases (COSMIC; cBioportal) list somatic POLH mutations that have been identified by sequencing genomic DNA from tumour tissues." (PMID 39457395, 2024). "Finally, POLH has been shown to exhibit the capacity to promote the RNA-templated error-free repair of DNA double-strand breaks (DSBs), a finding that has important implications for carcinogenesis and cancer therapy considerations." (PMID 38068959, 2023). "To validate the RNA-seq analysis, we selected seven representative genes on the basis of their relevance for HGSOC (PAX8, EGFR) and other cancers (GATA6, RBM47, KHDRBS3), or for their involvement in the DDR pathway (ATRIP, POLH)." (PMID 37202753, 2023). "Additional investigations have revealed that the co-inhibition of POLH and ATR, a protein that is central to the replicative stress response, offers an SL approach for the treatment of a range of cancer types." (PMID 38068959, 2023). "Additional investigations have revealed that co-inhibition of POLH and ATR, a protein central to the replicative stress response, offers a SL approach for the treatment of a range of cancer types." (PMID 34900730, 2021). "Among the differentially expressed genes in primary samples, 7 of 39 genes (VHL, GNE, POLH, MAPK13, NOP14, INADL, CDC5L) were reported to be cancer-related in the literature." (PMID 28009993, 2017). "In contrast to POLH, the POLK locus is highly deleted in cancers." (PMID 30347795, 2018).
tumor (8 papers, 2013 to 2025). "Fourth, tumor samples overexpressing POLH display a characteristic mutational signature known as “signature 9,” characterized by a preponderance of T>C and T>G substitutions." (PMID 34815340, 2021). "The aim of the present study was to identify the POLH mutation in an XP-V patient and to explore the roles of specific additional polymerases in XP-V tumor proneness." (PMID 24260050, 2013). "Few factors of tumor proneness in XP-V have been completely elucidated with the exception of the POLH [which encodes DNA polymerase η (pol η)] mutation." (PMID 24260050, 2013). "Although XP-V patients often suffer from a number of various types of skin cancer and a single case usually has more than one category of tumor, little is known concerning factors affecting tumor proneness in XP-V besides the POLH mutation." (PMID 24260050, 2013). "The present study reports a novel POLH mutation and its associated phenotypic features in an XP-V patient, as well as the expression of genes encoding pol η, ζ, κ, ι and θ in XP-V lip tumor cells, XP-V cell lines and HeLa cells in which POLH has been knocked down." (PMID 24260050, 2013). "When compared the top 20% of VEGFA expressing tumor samples to the bottom 20% expressing tumors and found that POLH goes up 1.69-fold (FDR 1 × 10−10), POLI goes up 2.06-fold (FDR 1.3 × 10−15) and REV3L goes up 1.62-fold (FDR 3.8 × 10−6)." (PMID 39468223, 2025). "Both tumors were reported as MSS from clinical testing and were hypermutated (POLD1/POLH tumor- 12.85 mut/Mb, POLE tumor- 14.44 mut/Mb)." (PMID 37095444, 2023). "Specifically, expression of POLK, POLQ and REV3L increased in the tumor cells while that of POLH, POLK, POLQ and REV3L decreased in the normal controls." (PMID 24260050, 2013). "The POLH gene was sequenced in the patient and the expression of pol η, ι, κ, θ and ζ was tested in XP-V tumor cells and cell lines, as well as in HeLa cells with POLH knockdown." (PMID 24260050, 2013). "We analyzed mutational signatures from the POLD1/POLH tumor and the POLE tumor." (PMID 37095444, 2023). "qPCR results revealed that the mRNA quantities of POLH, POLK, POLQ and REV3L in XP-V tumor cells were lower than those of the controls; however, the expression of POLI was higher in the XP-V tumor cells in the absence of UV irradiation (P<0.05)." (PMID 24260050, 2013). "In the present study, low expression of POLH, POLK and REV3L was observed in the XP-V tumor cells." (PMID 24260050, 2013). "Additionally, elevated AID/POLH-mediated mutagenesis and BCL6-IGH breakpoints in the IGH S region suggest that tumor cells may have undergone GC reactions." (PMID 40780199, 2025).
infection (3 papers, 2015 to 2024). The state of being infected such as from the introduction of a foreign agent such as serum, vaccine, antigenic substance or organism. "However, the major bottleneck of these systems is the lack of strong endogenous polymerase II dependent promoters, as the strong baculoviral p10 and polH promoters used in BEVS are only functional in presence of the viral transcription machinery during the late phase of infection." (PMID 26263512, 2015). "Under standardised infection conditions, VSV-G-induced syncytia were observed only in polH VSV-G BV, suggesting that all promoters displayed substantially reduced VSV-G levels as compared to hyperactive polH." (PMID 39339951, 2024). "Taken together, our results strongly suggest that while POLK, POLL and POLH are each capable of supporting cccDNA synthesis at a different efficiency during a de novo HBV infection, POLK plays a more dominant role under the infection conditions examined in this study." (PMID 27783675, 2016).
POLH also shares sentences with these, for which no sentence is quoted: -sensitive, (2 papers); B cell lymphomas (1); basal cell carcinoma (1); Cockayne syndrome (1); dyschromatosis symmetrica hereditaria (1); endometrial cancer (1); Erythema (1); genetic disease (1); hereditary cancer (1); lip (1); mucinous neoplasm (1); non-small cell lung carcinoma (1); prostate carcinoma (1); Thyroid Carcinoma (1); trichothiodystrophy (1); uterine corpus endometrial carcinoma (1); UV-sensitive syndrome (1); xeroderma pigmentosum variant type (1); xerosis (1).